MTCH1 (mitochondrial carrier 1)
Description:
Protein insertase that mediates insertion of transmembrane proteins into the mitochondrial outer membrane. Catalyzes insertion of proteins with alpha-helical transmembrane regions, such as signal-anchored, tail-anchored and multi-pass membrane proteins (By similarity). Does not mediate insertion of beta-barrel transmembrane proteins (By similarity). May play a role in apoptosis.
Synonyms: PSAP; CGI-64; SLC25A49; PIG60
Tractability: Antibody: UniProt predicts a signal peptide or a membrane-spanning region. PROTAC: ubiquitination databases record sites on it; its protein half-life has been measured.
Gene: Protein-coding gene on chromosome 6 (36,965,807 to 36,986,298, reverse strand). Ensembl gene ENSG00000137409.
Subcellular location: Mitochondrion outer membrane
Gene Ontology:
Molecular function: membrane insertase activity; protein binding
Biological process: positive regulation of apoptotic process; protein insertion into mitochondrial outer membrane; neuronal ion channel clustering; regulation of signal transduction
Cellular component: mitochondrion; membrane; mitochondrial outer membrane
Genetic constraint (gnomAD): Loss-of-function variants: 23 observed, 44.9 expected, observed/expected ratio (o/e) 0.51, 90% interval 0.37 to 0.73. The upper end of that interval is the gene's LOEUF score, 0.73, which puts it in group 2 of 6, group 1 being the genes least tolerant of losing a copy. Missense variants: 397 observed, 465.91 expected, observed/expected ratio (o/e) 0.85, 90% interval 0.78 to 0.93. Synonymous variants: 229 observed, 189.14 expected, observed/expected ratio (o/e) 1.21, 90% interval 1.09 to 1.35.
Homologues: Orthologues: chimpanzee MTCH1 (100% identical), macaque MTCH1 (99% identical), pig MTCH1 (99% identical), guinea pig MTCH1 (98% identical), mouse Mtch1 (98% identical), rat Mtch1 (98% identical), dog MTCH1 (71% identical), rabbit MTCH1 (66% identical), Drosophila melanogaster Mtch (29% identical), Drosophila melanogaster CG10920 (24% identical), Caenorhabditis elegans mtch-1 (22% identical), Caenorhabditis elegans F43E2.11 (8% identical). Paralogues in human: MTCH2 (37% identical).
Diseases named in the same sentence as MTCH1 in open-access papers:
MTCH1 is named in the same sentence as 20 diseases in open-access papers, as found by Europe PMC text mining. Sharing a sentence is not in itself a finding about the gene and the disease. The quoted sentences say what the papers report.
cervical cancer (5 papers, 2023 to 2025). A primary or metastatic malignant neoplasm involving the cervix. "GPX4 acts as a key anti-ferroptosis enzyme in cervical cancer, and its downregulation—triggered by MTCH1 deficiency and impaired FoxO1 nuclear translocation—leads to elevated ROS and ferroptotic cell death." (PMID 40895556, 2025). "We also demonstrated that the combination of MTCH1 deficiency with the clinical antitumor drug Sorafenib effectively and synergistically induce ferroptosis and suppress cervical cancer growth in a nude mouse xenograft model." (PMID 37550282, 2023). "A significant reduction in the tumor volume and weight was observed in the MTCH1 deficiency or Sorafenib-treated group compared with the control group, suggesting a role for MTCH1 in cervical cancer growth." (PMID 37550282, 2023). "Our results showed that the growth of human cervical cancers was markedly suppressed by MTCH1 deficiency, Sorafenib treatment and MTCH1 deficiency + Sorafenib treatment." (PMID 37550282, 2023). "By bioinformatics analysis and screening, we identified MTCH1 from a large number of mitochondrial localization proteins as being most closely associated with RFS of cervical cancer." (PMID 37550282, 2023). "In conclusion, our results suggested that MTCH1-deficiency impaired cervical cancer growth in vivo, and this effect was more pronounced when combined with Sorafenib." (PMID 37550282, 2023). "Targeting the MTCH1–FoxO1–GPX4 axis sensitizes cervical cancer cells to ferroptosis, offering a promising therapeutic strategy." (PMID 40895556, 2025). "Most notably, targeted MTCH1, when combined with Sorafenib, effectively and synergistically inhibited cervical cancer growth in a nude mouse xenograft model by actively inducing ferroptosis." (PMID 40821694, 2025). "It has been found that mitochondrial carrier 1 (MTCH1) is the central mediator of mitochondrial‐mediated ferroptosis in cervical cancer." (PMID 40821694, 2025). "Fourthly, targeting MTCH1 in combination with Sorafenib effectively and synergistically inhibited the growth of cervical cancer." (PMID 37550282, 2023). "Here, using an unbiased screening for mitochondrial transmembrane candidates, we identified mitochondrial carrier 1 (MTCH1) as a central mediator of MMF in cervical cancers." (PMID 37550282, 2023). "In the present study, through an unbiased bioinformatic screening strategy for mitochondrial transmembrane candidates, we identified mitochondrial carrier 1 (MTCH1) as a potential mitochondrial anti-ferroptosis factor in cervical cancers." (PMID 37550282, 2023). "Firstly, we expanded the biological functions of MTCH1 and delineated a novel molecular mechanism by which MTCH1 negatively regulated ferroptosis in cervical cancer cells." (PMID 37550282, 2023). "Strikingly, targeting MTCH1 in combination with Sorafenib effectively and synergistically inhibited the growth of cervical cancer in a nude mouse xenograft model by actively inducing ferroptosis." (PMID 37550282, 2023). "In order to explore more effective clinical treatment strategies and harness ferroptosis for therapeutic benefit, we targeted MTCH1 in combination with Sorafenib to fight against cervical cancer." (PMID 37550282, 2023). "Taken together, these previously unappreciated mechanistic insights that MTCH1 governs ferroptosis in cervical cancer open up new avenues for the development of anti-cancer drugs and strategies." (PMID 37550282, 2023). "Mitochondrial carrier 1 (MTCH1) is a central mediator of mitochondrial-mediated ferroptosis (MMF) in cervical cancer, and its deletion disrupts mitochondrial OXPHOS and initiates FoxO1-GPX4 axis-mediated retrograde signaling, which increases ROS and ultimately triggers ferroptosis." (PMID 38711526, 2024).
cervical cancer (continued). "Analysis of these SLC25 proteins in the Kaplan–Meier plotter database showed that the transcriptional levels of four candidate genes were correlated with relapse-free survival (RFS) of cervical cancer (P < 0.05), with MTCH1 had the most particularly pronounced effect (P < 0.01)." (PMID 37550282, 2023). "The growth and proliferation rate of cervical cancer cells with MTCH1 gene knockout was extremely low, and we found that they could not form tumors when transplanted into nude mice, suggesting that MTCH1 is critical for cervical cancer development." (PMID 37550282, 2023). "Altogether, these observations indicated that MTCH1 might serve as an attractive therapeutic target for cervical cancer." (PMID 37550282, 2023). "In conclusion, these findings enriched our understanding of the mechanisms of MMF in which MTCH1 governed ferroptosis though retrograde signaling to FoxO1-GPX4 axis, and provided a potential therapeutic target for treating cervical cancer." (PMID 37550282, 2023). "In addition, cervical cancer patients with low transcription of MTCH1 had a higher probability of RFS (HR = 5.18 (1.55–17.29), P = 0.0029), suggesting that low expression of MTCH1 possibly benefited cervical cancer patients and improved the prognosis." (PMID 37550282, 2023).
hepatocellular carcinoma (2 papers, 2021 to 2024). A malignant tumor that arises from hepatocytes. "SM suppresses hepatocellular carcinoma growth by reducing STAT1-mediated MTCH1 expression, thereby inducing apoptosis and ferroptosis." (PMID 39315094, 2024). "Gene chip and RNA-seq data displayed that, compared to normal tissues, MTCH1 expression was increased in liver carcinoma tissues (P < 0.001)." (PMID 34195286, 2021). "The data revealed that MTCH1 expression was largely heightened in three types of carcinomas, containing liver carcinoma, pancreas carcinoma, and uterine carcinoma, but decreased in 13 types of carcinomas tissues, such as Acute Myeloid Leukemia (AML) and breast carcinoma." (PMID 34195286, 2021). "Our result implied that MTCH1 was a probably useful biomarker for the diagnosis of liver carcinoma." (PMID 34195286, 2021).
liver cancer (2 papers, 2021 to 2023). An epithelial or non-epithelial malignant neoplasm that arises from the liver. "Notably, a recent study shows that up-regulation of MTCH1 expression is associated with the proliferation, invasion and migration of liver cancer cells, suggesting that MTCH1 may have other potential new functions in cancer." (PMID 37550282, 2023).
fibromyalgia (1 paper, 2014). A chronic disorder of unknown etiology characterized by pain, stiffness, and tenderness in the muscles of neck, shoulders, back, hips, arms, and legs. "Fibromyalgia has been genetically linked to the HLA region (6p21.3) 63, which includes several genes associated with Notch signalling (e.g. Notch4, FKBP5, TNXB, MTCH1 and TNF-a) or with stem cell maintenance and proliferation (e.g. POU5F1, Flot1, MAPK14, Rgl2 and Rab44)." (PMID 25164209, 2014).
Right ventricular cardiomyopathy (1 paper, 2016). Right ventricular dysfunction (global or regional) with functional and morphological right ventricular abnormalities, with or without left ventricular disease. "Also of interest is the plakophilin 2 gene (PKP2), associated with right ventricular cardiomyopathy and multiple genes involved in mitochondrial energy metabolism (MTCH1, OXA1L, MUL1)." (PMID 27923400, 2016).
thalassemia (1 paper, 2022). An inherited blood disorder characterized by a decreased synthesis of one of the polypeptide chains that form hemoglobin. "Increased cell death was distinctly present only in homozygous β0-thalassemia erythroblasts and associated with the up-regulation of pro-apoptotic (Caspase 9, BAD, and MTCH1) genes and down-regulation of the anti-apoptotic BCL-XL gene." (PMID 36143003, 2022).
tumor (4 papers, 2018 to 2023). "Tumor metastasis often means advanced tumor stage and tumor deterioration, so we analyzed the association between the expression of MTCH1 and tumor stage by the GEPIA database." (PMID 34195286, 2021). "Additionally, our data indicated that higher expression of MTCH1 exhibited an association with metastasis of neoplasm, stage of carcinoma, and poor survival of LIHC patients." (PMID 34195286, 2021). "To analyze MTCH1 expression profiles in normal and tumor tissues, we conducted the TNMplot online tool." (PMID 34195286, 2021). "Among 369 LIHC tumor samples and 50 normal samples, it was found that compared to normal samples, tumor samples were highly expressed MTCH1." (PMID 34195286, 2021). "Thus, we compromisingly utilized the MTCH1 knockdown cell line to establish a nude mouse tumor-bearing model." (PMID 37550282, 2023). "Finally, we detected an increase in the presentation of a tumor-specific neoantigen derived from Mtch1." (PMID 36089194, 2022). "Given that Sorafenib is a multi-target drug and ferroptosis inducible antitumor agent, and that MTCH1 inactivation triggers ferroptosis, we investigated whether targeting MTCH1 in combination with Sorafenib could produce an additive effect on inhibiting tumor growth." (PMID 37550282, 2023). "Based on multiple public databases, we analyzed the high expression of MTCH1 in LIHC, and its high expression is closely related to tumor metastasis, tumor staging, and poor patient quality of life." (PMID 34195286, 2021). "Next, we in-depth validated MTCH1 expression in metastatic tissues, and our data indicated MTCH1 expression was greatly higher in metastatic tumor tissues, compared to that in nonmetastatic tumor tissues and normal tissues." (PMID 34195286, 2021). "Finally, we validated their expression using qPCR in an additional set of tumor:matched normal samples that resulted in five genes (RPL30, RPL27, PSMC5, MTCH1, and OAZ1), out of which RPL30 and RPL27 were most stable and were abundantly expressed across the tissues." (PMID 30128175, 2018).
cancer (3 papers, 2021 to 2025). A tumor composed of atypical neoplastic, often pleomorphic cells that invade other tissues. "It inhibits the proliferation of HCC cells by promoting the STAT1/MTCH1 axis in cancer cells, while also inducing apoptosis and ferroptosis." (PMID 40386780, 2025). "Here, we provided strong evidence to link MTCH1 with ferroptosis and cancer growth, and explored potential mechanisms and clinical applications." (PMID 37550282, 2023). "For the first time, our results suggested that MTCH1 was aberrantly expressed in human pan-cancer and highly expressed in LIHC." (PMID 34195286, 2021). "Here, we employed the Kaplan Meier Plotter online tool to investigate the MTCH1 expression profile in human pan-cancer." (PMID 34195286, 2021). "Previous reports have shown that MTCH1 is vital in apoptosis, suggesting that it displays importance in carcinoma." (PMID 34195286, 2021). "Our study for the first time explores the MTCH1 expression profile in twenty-two types of carcinomas by TNMplot databases." (PMID 34195286, 2021). "Our results suggested that MTCH1 expression was abnormal in human pan-cancer." (PMID 34195286, 2021). "Nevertheless, it is still elusive towards the part of MTCH1 in human carcinomas." (PMID 34195286, 2021). "There were few types of carcinomas used for the study of MTCH1 expression." (PMID 34195286, 2021).
head and neck tumor (1 paper, 2018). "Our data suggest that RPL30 or RPL27 in combination with either PSMC5 or MTCH1 or OAZ1 can be used as a minimal set of control genes in head and neck tumor gene expression studies." (PMID 30128175, 2018).
MTCH1 also shares sentences with these, for which no sentence is quoted: Sepsis (4 papers); acute myeloid leukemia (1); Alzheimer disease (1); breast carcinoma (1); cardiomyopathy (1); heart failure (1); hypertrophy (1); Pan (1); pancreas carcinoma (1); uterine carcinoma (1); virus infection (1).